LINC01767 (long independently transcribed non-coding RNA 1767)
Synonyms: CRLM1
Gene: Long non-coding RNA gene on chromosome 1 (56,414,918 to 56,417,137, forward strand). Ensembl gene ENSG00000223956.
Diseases named in the same sentence as LINC01767 in open-access papers:
LINC01767 is named in the same sentence as 2 diseases in open-access papers, as found by Europe PMC text mining. Sharing a sentence is not in itself a finding about the gene and the disease.
LINC01767 shares sentences with these, for which no sentence is quoted: cancer (1 paper); tumor (1).